TSNARE1 (t-SNARE domain containing 1)
Synonyms: FLJ31164
Tractability: Antibody: UniProt predicts a signal peptide or a membrane-spanning region. PROTAC: ubiquitination databases record sites on it.
Gene: Protein-coding gene on chromosome 8 (142,212,077 to 142,403,213, reverse strand). Ensembl gene ENSG00000171045.
Subcellular location: Membrane
Subcellular location (Human Protein Atlas): Cytosol
Gene Ontology:
Molecular function: SNARE binding
Biological process: vesicle-mediated transport
Cellular component: synaptic vesicle; membrane
Genetic constraint (gnomAD): Loss-of-function variants: 49 observed, 60.23 expected, observed/expected ratio (o/e) 0.81, 90% interval 0.65 to 1.03. The upper end of that interval is the gene's LOEUF score, 1.03, which puts it in group 4 of 6, group 1 being the genes least tolerant of losing a copy. Missense variants: 755 observed, 690.44 expected, observed/expected ratio (o/e) 1.09, 90% interval 1.03 to 1.16. Synonymous variants: 328 observed, 292.41 expected, observed/expected ratio (o/e) 1.12, 90% interval 1.02 to 1.23.
Homologues: Orthologues: chimpanzee TSNARE1 (99% identical), macaque TSNARE1 (87% identical), dog TSNARE1 (65% identical), tropical clawed frog tsnare1 (29% identical), zebrafish tsnare1 (25% identical), Drosophila melanogaster Syx13 (12% identical). Paralogues in human: STX12 (15% identical), STX7 (14% identical), STX16 (12% identical), STX5 (10% identical), STX2 (9% identical), STX3 (8% identical), STX4 (8% identical), STX1A (8% identical), STX1B (8% identical), STX17 (7% identical), STX19 (7% identical), STX11 (7% identical).
Diseases named in the same sentence as TSNARE1 in open-access papers:
TSNARE1 is named in the same sentence as 14 diseases in open-access papers, as found by Europe PMC text mining. Sharing a sentence is not in itself a finding about the gene and the disease. The quoted sentences say what the papers report.
schizophrenia (11 papers, 2015 to 2024). A major psychotic disorder characterized by abnormalities in the perception or expression of reality. "Another interesting variant was identified in affected siblings MC-24-3 and MC-24-4, in an enhancer region that interacts with the promoters of TSNARE1, a gene associated with schizophrenia, and ADGRB1, a critical regulator of spine and synapse development." (PMID 35190550, 2022). "TSNARE1 gene has been previously associated with schizophrenia and rate of cognitive decline in late MCI." (PMID 31477183, 2019). "A recent GWAS meta-analysis of psychiatric disorders identified TSNARE1 as susceptibility gene for schizophrenia, schizoaffective and bipolar disorders." (PMID 25950944, 2015). "TSNARE1 (8q24.3) has previously been implicated in schizophrenia and cognitive function." (PMID 32152294, 2020). "Based on the GWAS results, we detected two SNPs; rs12675715 and rs13262595 that are located in TSNARE1, a gene that encodes the tSNARE1 (t-SNARE containing domain 1) protein, which is associated with schizophrenia onset and bipolar disorder." (PMID 37982563, 2024). "The Mann–Whitney U‐test revealed that patients with schizophrenia had a significant change in plasma anti‐TSNARE1 and anti‐CD25 IgG levels; male patients mainly contributed to the increased levels of anti‐TSNARE1 IgG and anti‐CD25 IgG." (PMID 31336035, 2019). "The present study demonstrated that patients with schizophrenia had a significant increase in circulating anti‐TSNARE1 IgG levels, and male patients mainly contributed to the altered IgG levels." (PMID 31336035, 2019). "Two separate cQTLs in MAD1L1 (PP(H4) > 0.98), one cQTL in AS3MT (PP(H4) = 0.98), one cQTL in TSNARE1 (PP(H4) = 0.94), and one cQTL in RERE (PP(H4) = 0.92) were found to colocalize with schizophrenia-associated variants." (PMID 30087329, 2018). "Other schizophrenia risk loci with TCF4 binding sites include DRD2, TSNARE1, and GRIA1, all of which are down-regulated in TCF4-depleted cells and MIR137/DPYD." (PMID 29228394, 2018). "Dysregulation of the genes FURIN, TSNARE1, CNTN4, CLCN3 and SNAP91 have been implicated by eQTL analysis of schizophrenia GWAS hits, which were later separately prioritized by chromatin interaction analysis of schizophrenia risk variants." (PMID 35972862, 2022). "We conclude that there is a gender difference in autoimmune responses in schizophrenia and suggest that anti‐TSNARE1 IgG may be indicative of schizophrenia in a subgroup of male patients." (PMID 31336035, 2019). "It is worth noting that the anti‐TSNARE1 IgG assay has the highest sensitivity (true positive) of 15.7% (19.3% in males) against a specificity (true negative) of 95.2%, suggesting that anti‐TSNARE1 IgG may be indicative of a subgroup of schizophrenia." (PMID 31336035, 2019).
atherosclerosis (1 paper, 2019). A disease characterized by the build-up of fatty material and calcium deposition in the arterial wall resulting in partial or complete occlusion of the arterial lumen. "Other CpGs in the genes NOD2 and TCP11L1 have been linked to atherosclerosis, and in the TSNARE1 gene, with CRP." (PMID 31212707, 2019).
epilepsy (1 paper, 2015). A brain disorder characterized by episodes of abnormally increased neuronal discharge resulting in transient episodes of sensory or motor neurological dysfunction, or psychic dysfunction. "These microdeletions affected 158 protein-coding RefSeq genes and exhibited an enrichment of genes previously associated with epilepsy (NRXN1, RBFOX1, PCDH7, KCNA2, EPM2A, RORB, PLCB1) and neuropsychiatric disorders (DPYD, CADM2, PARK2, GRM8, TSNARE1, TPH2, MACROD2)." (PMID 25950944, 2015).
mastitis (1 paper, 2024). Inflammation of breast tissue during lactation or postpartum due to an obstructed duct or infection. "Among them, cnvr_137 contains genes such as LY6D, LYNX1, LYPD2, SLURP1,THEM6, PSCA, TSNARE1, and ARC associated to clinical mastitis in US Holstein dairy cows." (PMID 38771855, 2024).
multiple sclerosis (1 paper, 2015). A progressive autoimmune disorder affecting the central nervous system resulting in demyelination. "Additionally, three were associated with neurological disorders or functions including SZ (rs4129585 at TSNARE1), multiple sclerosis (rs12644284 at TRIM2) and brain structure (rs12479254 at BOK)." (PMID 25990720, 2015).
TSNARE1 also shares sentences with these, for which no sentence is quoted: bipolar disorder (2 papers); behavioral disorder (1); cognitive decline (1); insomnia (1); neurological disorders (1); parasite infection (1); psychiatric disorder (1); psychosis (1); sleep disorder (1).